ALK (ALK receptor tyrosine kinase)
Diseases named in the same sentence as ALK in open-access papers (continued):
Sharing a sentence is not in itself a finding about the gene and the disease.
medulloblastoma (8 papers, 2011 to 2024). A malignant, invasive embryonal neoplasm arising from the cerebellum. "Previous studies investigating hotspot mutations in exons 23 and 25 estimate that ALK alterations occur in around 1–2% of medulloblastoma tumors." (PMID 38339401, 2024). "Nevertheless, previous findings suggest that ALK assessment is of diagnostic and prognostic value in medulloblastoma (WNT-activated)." (PMID 38339401, 2024). "Immunohistochemical detection of ALK has been postulated to be of significant value in the identification of WNT-activated medulloblastomas, complementing methods like CTNNB1 gene mutation and β-catenin nuclear reaction analysis." (PMID 38339401, 2024). "One patient with ALK variant (#2) and medulloblastoma suffered from postoperative mutism (posterior fossa syndrome)." (PMID 38139220, 2023). "Therefore, the fact that ALK expression is positive in APC mutated tumor reinforces the usefulness of this marker for detection of the WNT type of medulloblastoma." (PMID 30523493, 2019). "These could target the defective DNA damage repair in the LFS-associated medulloblastoma, the prolactin autocrine loop in the atypical prolactinoma, the EPHA3/7 and ALK overexpression in the FAP-associated medulloblastoma, and the multi-RTK upregulation in the soft tissue neoplasms." (PMID 35978432, 2022). "Analysis of ALK expression holds significant value in medulloblastoma, particularly for identifying WNT-activated tumors." (PMID 38339401, 2024). "Following this, in the present study, we extended analysis on additional 55 medulloblastomas, with a focus on ALK positive cases." (PMID 30523493, 2019). "Expression of the ALK gene strongly correlates with the WNT-activated medulloblastomas, which are routinely identified by detection of CTNNB1 mutation." (PMID 30523493, 2019). "Among 55 medulloblastomas, 6 tumors showed ALK expression in > 50% of tumor cells." (PMID 30523493, 2019). "Overall 55 medulloblastomas were analyzed by immunohistochemistry for ALK expression." (PMID 30523493, 2019). "Overall, ALK’s role in medulloblastoma may differ from its function in other tumors in children." (PMID 38339401, 2024). "Additional findings suggest that ALK protein expression alone could be an indicator of a favorable prognosis for medulloblastoma patients and that ALK expression could be a crucial marker for identifying WNT-activated medulloblastoma tumors, including those in the cerebellopontine angle (CPA)." (PMID 38339401, 2024). "As already mentioned, ALK protein might have a role in the development of medulloblastoma." (PMID 38139220, 2023). "In addition, we examined if the ALK protein expression may differentiate WNT-activated medulloblastomas from other histologically misleading high grade malignancies located in the posterior fossa in pediatric cases." (PMID 30523493, 2019). "Based on our results, we indicate that ALK protein expression may easily differentiate WNT-activated medulloblastomas from other histologically similar high-grade pediatric tumors located in the posterior fossa (cerebellum/fourth ventricle/ cerebellopontine angle)." (PMID 30523493, 2019). "In addition, we examined if ALK expression may differentiate WNT-activated medulloblastoma from other malignant posterior fossa tumors." (PMID 30523493, 2019). "In summary, we propose that the immunohistochemical detection of ALK protein should be routinely investigated, in parallel to already established methods for identification of WNT-activated medulloblastomas." (PMID 30523493, 2019). "As we showed previously, a strong correlation exists between the presence of ALK expression and the WNT type of medulloblastoma, both at the RNA and protein levels." (PMID 30523493, 2019). "Therefore, we propose, that immunohistochemical detection of ALK protein should be highly recommended in routine investigation, in parallel to already established methods for identification and differentiation of WNT-activated medulloblastoma." (PMID 30523493, 2019).
metastatic carcinoma (8 papers, 2017 to 2025). A carcinoma which has spread from the original site of growth to another anatomic site. "In the phase 1 ASCEND-1 study, ceritinib demonstrated activity in ALK-rearranged locally advanced or metastatic cancer NSCLC patients, including both ALK-naïve and ALK-pretreated patients who had progressed following multiple lines of chemotherapy." (PMID 28424757, 2017). "For these metastatic cancer patients, targeted therapy such as EGFR and ALK inhibitors have been developed, but they only show favorable efficiency to specific patients with EGFR and ALK mutations." (PMID 37583701, 2023). "The studies evaluated both the safety and efficacy of orally administering entrectinib to adults with locally advanced metastatic cancer with NTRK1, NTRK2, NTRK3, ROS1, or ALK rearrangements." (PMID 37111737, 2023). "The ALKA-372-001, STARTRK-1, and STARTRK-2 studies evaluated both the safety and efficacy of orally administering entrectinib to adult patients with locally advanced metastatic cancer with NTRK1, NTRK2, NTRK3, ROS1, or ALK rearrangements." (PMID 37111737, 2023).
pericardial effusion (8 papers, 2015 to 2025). Fluid collection within the pericardial sac, usually due to inflammation. "This study highlights the significant association between ALK inhibitors and the development of pleural and pericardial effusions, with notable variability across individual agents." (PMID 40828781, 2025). "Disproportionality analyses using global pharmacovigilance databases, such as VigiBase and FAERS, have provided evidence linking ALK inhibitors to cardiovascular toxicities, including pericarditis and associated pericardial effusions." (PMID 40828781, 2025). "The findings of this study emphasize a significant association between ALK inhibitors and the development of pleural and pericardial effusions, with notable variability among individual drugs." (PMID 40828781, 2025). "Despite their proven efficacy in prolonging progression-free and overall survival, ALK inhibitors are associated with notable adverse events, particularly cardiopulmonary complications such as pleural and pericardial effusions." (PMID 40828781, 2025). "Statistical data showing the association between ALK inhibitors and pleural/pericardial effusions." (PMID 40828781, 2025). "At present, there was one case report on pericardial effusion caused by alectinib, but more case reports have shown that the symptoms of pericardial effusion can be effectively improved using ALK-TKIs." (PMID 35370632, 2022). "Judging from the 11 types of PT, pericardial effusion occurred in all four ALK-TKIs, and the correlation of these AEs was stronger than that of other types of PT associated with cardiac AEs according to ROR ranking." (PMID 35370632, 2022). "Additionally, because FAERS data is observational, it cannot establish causality, only associations, necessitating cautious interpretation of potential links between ALK inhibitors and pleural or pericardial effusions." (PMID 40828781, 2025). "For conventional CT features, pericardial effusion, local lymphadenopathy, lobulated margin, and the absence of pleural retraction sign were selected in both the radiological and integrated model as being correlated with ALK-rearranged status." (PMID 32266148, 2020). "Notably, pleural and pericardial effusions emerged as class-wide signals across all ALK-TKIs." (PMID 40137538, 2025). "Moreover, the symptoms of pericardial effusion could be effectively improved by other ALK-TKIs." (PMID 38903993, 2024). "PBL is distinguished from ALK-positive DLBCL by its lack of expression of the ALK protein, and the absence of HHV8 co-infection distinguishes PBL from PEL which usually manifests as pleural or pericardial effusion and rarely associates with lymphadenopathy or mass." (PMID 26108914, 2015).
renal tumors (8 papers, 2019 to 2024). "Since then, there has been a rapid expansion of molecularly defined renal tumors and a willingness to consider ALK-RCC in the differential of difficult-to-classify renal tumors." (PMID 39205743, 2024). "This case taught us the importance of considering the possibility of ALK-RCC in the pathological diagnosis of unusual renal tumors." (PMID 35718773, 2022). "In kidney, renal tumors with ALK rearrangement have also been rarely reported." (PMID 31905821, 2019). "We strongly recommend that ALK-IHC be routinely performed for renal tumors with negative AMACR staining that mimic MTSCC." (PMID 35718773, 2022). "In recent years, the increasing understanding of RCC genetics has led to the identification of potential new renal tumor entities, classified as “emerging or provisional” in the recent “WHO classification of tumors of the urinary system and male genital organs”, including the ALK-RCC subtype." (PMID 35409355, 2022).
schwannoma (8 papers, 2016 to 2025). A benign, usually encapsulated slow growing tumor composed of Schwann cells. "Indeed, we would not have anticipated a drug known for its ability to inhibit ALK demonstrating preclinical efficacy in either NF2 associated schwannoma or meningioma." (PMID 34264955, 2021). "We confirmed that brigatinib had efficacy comparable to ALK-IN-1 in slowing the growth of schwannoma and meningioma cells lines and also exhibited modest in vitro synergy in growth inhibition of meningioma cells when combined with MK-2206." (PMID 34264955, 2021). "These efforts identified brigatinib (ALUNBRIG®), an FDA-approved inhibitor of multiple tyrosine kinases including ALK, to be a potent inhibitor of tumor growth in established NF2 deficient xenograft meningiomas and a genetically engineered murine model of spontaneous NF2 schwannomas." (PMID 34264955, 2021). "Interestingly, neither Merlin-deficient schwannoma nor meningioma cells express the primary published target of brigatinib, anaplastic lymphoma kinase (ALK)." (PMID 34264955, 2021). "The most effective combinations in Schwann cells were slightly different and included: ALK-IN-1/dasatinib, TAE226 (a dual FAK/IGF-1R inhibitor)/dasatinib, and dasatinib/simvastatin (an HMG-CoA reductase inhibitor) for schwannoma." (PMID 34264955, 2021). "In our analysis, we observed that the markers SMA, Desmin, CD117, DOG-1, ALK, Synaptophysin, Chromogranin and AE1/AE3 stained negatively in all analyzed schwannomas." (PMID 30710876, 2019). "For example, GISTs are positive for CD117, schwannomas are positive for S100 protein, and IMTs are positive for ALK and negative for CD34, whereas IFPs are not." (PMID 29855265, 2018). "Surprisingly, neither meningioma nor schwannoma cells express ALK." (PMID 34264955, 2021).
synovial sarcoma (8 papers, 2018 to 2024). "Using phosphoproteomic profiling, MET and ALK have been identified as novel targets of synovial sarcoma and are highly expressed in 58% and 14% of ES patients, respectively." (PMID 32754598, 2020). "MET and ALK expression are involved in the pathogenesis of ES and synovial sarcoma." (PMID 32754598, 2020). "Since PI3K was shown to be regulated by both ALK and MET signals in some tumor cells, selective induction of apoptosis in synovial sarcoma cells was mediated by abrogating these aberrant tyrosine kinase signals." (PMID 30416685, 2018). "Focusing on the synovial sarcoma subtype, they found several new RTK dependencies including ALK, PDGFRα and MET which were functionally tested in preclinical in vivo experiments and whose expression was shown to be elevated in a subset of synovial sarcoma patient specimens." (PMID 35171456, 2022). "It was reported that the synovial sarcoma Aska-SS cell line expressed an activated ALK variant and showed sensitivity to ALK inhibitors, while another synovial sarcoma cell line Yamato-SS overexpressed MET protein and exhibited sensitivity to the ALK/MET dual inhibitor, crizotinib." (PMID 30416685, 2018).
thyroid tumor (8 papers, 2014 to 2025). A benign or malignant neoplasm affecting the thyroid gland. "These rearrangements typically involve NTRK1, NTRK3, or ALK, with various fusion partners, and have been shown to induce thyroid tumors in vivo." (PMID 41175860, 2025). "The 75 thyroid tumors series study revealed that 2 among 16 conventional PTC exhibited a STRN/ALK fusion." (PMID 24475247, 2014). "FISH revealed that 52% of primary thyroid tumor cells and 66% of lung metastasis carcinoma cells presented an unbalanced rearrangement of the ALK gene." (PMID 24475247, 2014). "ALK is the third major tyrosine kinase gene commonly rearranged in thyroid tumors." (PMID 41175860, 2025). "In order to test whether the STRN/ALK fusion is recurrent in thyroid tumors, 75 thyroid samples of various histotypes were screened by RT-PCR." (PMID 24475247, 2014). "A rearrangement of the anaplastic lymphoma kinase (ALK) gene was detected using FISH both in the well-differentiated and anaplastic components of the thyroid tumor and in the anaplastic lung metastases." (PMID 24475247, 2014).
COVID-19 (7 papers, 2020 to 2025). A disease caused by infection with severe acute respiratory syndrome coronavirus 2. "This analysis of real-word patient data evaluated the characteristics and the current diagnostic landscape of patients with EGFR/ALK mNSCLC across five European countries, and the impact of COVID-19 on the treatment and management of this population." (PMID 37386452, 2023). "Investigating the impact of COVID-19 on the treatment of patients with EGFR-WT/ALK-WT mNSCLC, there was indication of delays in diagnosis during COVID-19, but with no apparent change in the tests and assessments used." (PMID 37386452, 2023). "After excluding death, malignancy-related AEs, and COVID-19, a total of 454 statistically significant AE signals were identified across the five ALK-TKIs: crizotinib (104 signals), ceritinib (89 signals), alectinib (94 signals), brigatinib (52 signals), and lorlatinib (115 signals)." (PMID 40137538, 2025). "One case of each EGFR, ALK, ROS1, and BRAF genetic alteration were found in the COVID-19 patients." (PMID 33042826, 2020).
diabetes (7 papers, 2021 to 2025). "Diabetes prevalence varied from 11.5% among patients treated with ALK inhibitors (26 patients) to 26.7% among patients treated with MET inhibitors (8 patients)." (PMID 41196597, 2025). "In our case report, we describe a case of lorlatinib-induced hyperglycemia and DKA in a patient with ALK-positive NSCLC with no prior history of diabetes mellitus and who was found to be antibody-negative." (PMID 41322009, 2025). "For the assessment of tumor response to ALK inhibition in vivo, we employed immunocompromised nonobese diabetes/severe combined immunodeficiency animals, inoculated with SW48 (CMS1) cells and then randomized into two groups: vehicle control and CZB (50 mg/kg/day)." (PMID 35351152, 2022). "Here, we describe a case of lorlatinib-induced DKA in a patient with ALK-positive NSCLC and no prior history of diabetes mellitus." (PMID 41322009, 2025).
endometrial cancer (7 papers, 2015 to 2025). Primary or metastatic malignant neoplasm involving the endometrium (mucous membrane that lines the endometrial cavity). "Overexpression of ALK is associated with higher tumor grade, enhanced stemness, EMT, migration, and proliferation, as well as decreased apoptosis, in endometrial cancer." (PMID 40429950, 2025). "To test this, we hereby investigated the expression of ALK, as well as the profiles of its related molecules, using endometrial carcinoma (Em Ca) cell lines and clinical UCS samples." (PMID 28193280, 2017). "The conclusion is supported by further investigation using endometrial carcinoma cell lines with overexpression of endogenous full-length ALK, since carcinoma cell lines that naturally harbor full-length ALK are in general extremely rare." (PMID 28193280, 2017). "Similarly, endometrial cancer progression has been demonstrated to be correlated with the expression of known MDK receptors such as ALK and Notch2." (PMID 40429950, 2025). "Regulation and function of the ALK gene were assessed using two endometrial carcinoma cell lines." (PMID 28193280, 2017). "Although anaplastic lymphoma kinase (ALK) is overexpressed in several primary solid tumor types, its role in endometrial carcinoma (Em Ca) remains unclear." (PMID 37592266, 2023).
leiomyoma (7 papers, 2017 to 2025). A well-circumscribed benign smooth muscle neoplasm characterized by the presence of spindle cells with cigar-shaped nuclei, interlacing fascicles, and a whorled pattern. "All tested cases (5/5, 100%) showed ALK gene rearrangement, including 3 cases that were negative for ALK protein expression by immunohistochemistry, 1 case exhibiting a leiomyoma-like histological pattern, and 1 case of EIMS." (PMID 41179654, 2025). "Recent research has shown that 0.3% of unselected leiomyomas were reclassified as IMTs based on positive anaplastic lymphoma kinase (ALK) immunohistochemistry (IHC), even though routine ALK screening for the diagnosis of leiomyomas is not currently recommended." (PMID 39372869, 2024). "Among the 8 cases of IMT with unusual features in our series, FISH analysis was performed on 5 cases, including 3 cases of ALK-negative IMT, 1 case of pure leiomyoma-like IMT, and 1 case of EIMS." (PMID 41179654, 2025).
Obesity (7 papers, 2021 to 2024). Accumulation of substantial excess body fat. "As already mentioned, genetic deletion of ALK caused thinness in mice with clear resistance to diet-induced obesity." (PMID 37432348, 2023). "That loss of ALK protected against diet-induced obesity highlighted its ability to restrain lipolysis and maintain adipose tissue storage by controlling sympathetic tone (norepinephrine output)." (PMID 37414143, 2023). "Moreover, loss of ALK protects mice from diet- and leptin (mutation)-induced obesity in a manner involving its hypothalamic control of energy expenditure via adipose tissue lipolysis." (PMID 37414143, 2023). "Knockout mice of augmentor-α exhibit a similar thinness phenotype and resistance to diet-induced obesity of ALK knockout mice." (PMID 37432348, 2023). "Recently, it has been shown that genetic deletion of ALK resulted in thin mice with marked resistance to diet-induced obesity and increased energy expenditure." (PMID 37432348, 2023). "Recently, a genetic deletion of ALK in mice has been found to increase energy expenditure and confers resistance to obesity in these animals, suggesting its role in the regulation of thinness." (PMID 37432348, 2023). "Surprisingly, ALK-deficient mice do not present major behavioral deficits besides thinness due to decreased triglyceride levels and resistance to diet-induced obesity." (PMID 35608912, 2022). "Further characterization of the mechanisms by which SCD-2 and ALK regulate food-dependent behavior, gene expression, and metabolism could reveal new factors governing body weight and have implications in the treatment and prevention of obesity." (PMID 38231572, 2024).
plasmacytoma (7 papers, 2012 to 2021). Plasmacytoma is a localized mass of neoplastic monoclonal plasma cells that represents approximately 5% of all plasma cell neoplasms. "In vivo, nucleophosmin-ALK expression during transgenic IL-9 expression led to the development of murine plasmacytoma, plasmoblastic/anaplastic lymphoma and precursor T-lymphoblastic lymphoma." (PMID 24722378, 2014). "MYC rearrangement by FISH analysis might be considered as a part of the diagnostic work-up, as MYC rearrangement is most often associated with plasmablastic lymphoma and anaplastic plasmacytoma, but absent in ALK-positive large B-cell lymphoma and PEL." (PMID 33669719, 2021).